COL4A2 (collagen type IV alpha 2 chain)
Diseases named in the same sentence as COL4A2 in open-access papers (continued):
Sharing a sentence is not in itself a finding about the gene and the disease.
keloid (2 papers, 2018 to 2019). An irregularly shaped, elevated mark on the skin caused by deposits of excessive amounts of collagen during wound healing. "sNskin was usually intermediate between normal skin and keloid in the expression of scar parameters and often similar to the peripheral keloid model (contraction; α-SMA expression; secretion of HGF; expression of COL4A2)." (PMID 30370495, 2018). "The baseline keloid model comprising the entire keloid showed no increase in epidermal thickness, but reduced COL4A2, HAS1 and MMP3 gene expression in the dermal compartment of the keloid model compared to the normal skin model." (PMID 30370495, 2018).
liver cancer (2 papers, 2020 to 2024). An epithelial or non-epithelial malignant neoplasm that arises from the liver. "Splice variants for COL4A2 are co-up-regulated in the liver cancer tumors." (PMID 38374893, 2024). "Over expression of COL4A2 is highly related to shorter progression-free survival in patients with liver cancer." (PMID 38374893, 2024). "Based on 4 genes (COMP, SPP1, COL4A2, and ITGAV) in the pathway of integrin cell surface interactions, a risk score model for prognosis of liver cancer was constructed." (PMID 38374893, 2024). "A correlation analysis of COL4A2 showed that the overexpression of COL4A2 was highly correlated with shorter progression-free survival in liver cancer." (PMID 32704448, 2020). "COL4A2 is a significantly upregulated gene in liver cancer cells." (PMID 38374893, 2024). "Thus, it can be seen that COMP, SPP1, and COL4A2 play important roles in the development of liver cancer." (PMID 38374893, 2024). "The risk score model constructed by genes (COMP, SPP1, COL4A2, and ITGAV) in the pathway of integrin cell surface interactions may be used to predict survival in liver cancer patients." (PMID 38374893, 2024). "It is indicated that the association between ITGAV, SPP1, COL4A2, COMP, and immune cells may be involved in the progression of liver cancer." (PMID 38374893, 2024). "In addition, ROC analysis showed that ITGAV, SPP1, COL4A2, and COMP had a potential diagnostic value for liver cancer patients." (PMID 38374893, 2024). "In pathway of integrin cell surface interactions, COL4A2, COMP, ITGAV, and SPP1 were used to perform LASSO Cox regression analysis to construct the prediction model of the overall survival rate of liver cancer patients in the TCGA database." (PMID 38374893, 2024). "The mRNA expression levels of COL4A2, COMP, ITGAV, and SPP1 were significantly increased in liver cancer tissues." (PMID 38374893, 2024). "COL4A2 and SPP1 were significantly upregulated in liver cancer tissues." (PMID 38374893, 2024).
myopia (2 papers, 2019 to 2026). "COL4A2 is downregulated in FDM choroid, and suppression of COL4A2 impairs the choroid vascular scaffold and promotes myopia shift with decreased choroidal thickness." (PMID 41823499, 2026). "Collagen type IV alpha 2 chain (COL4A2) related disease was also suggested as an adult onset SVD, where similar phenotypes were present, such as porencephaly, scattered white matter lesions, carotid aneurysm, myopia, amblyopia, cerebellar- and visual abnormalities." (PMID 31484286, 2019).
osteoarthritis (2 papers, 2021 to 2023). A noninflammatory degenerative joint disease occurring chiefly in older persons, characterized by degeneration of the articular cartilage, hypertrophy of bone at the margins and changes in the synovial membrane. "In summary, several lines of evidence suggest a role for Col4a2 in the pathogenesis of osteoarthritis and the articular cartilage damage in Col4a2−/− mice is consistent with this hypothesis." (PMID 33473114, 2021).
osteoporosis (2 papers, 2005 to 2022). A condition of reduced bone mass, with decreased cortical thickness and a decrease in the number and size of the trabeculae of cancellous bone (but normal chemical composition), resulting in increased fracture incidence. "By searching for references in PubMed we discovered that 9 of these genes (~ 15% of the total) are already candidates for involvement in diseases including Alzheimers (ABCA2), osteoporosis (COL4A1 and COL4A2) and schizophrenia (SLIT3)." (PMID 15766383, 2005). "Furthermore, the generally acidic osteoporotic bone in untreated osteoporosis could support bone metastasis with the secretion of proteins such as COL1A1, COL4A2, NID1, FBLN1, and NRP2." (PMID 35159353, 2022).
osteosarcoma (2 papers, 2024 to 2025). A usually aggressive malignant bone-forming mesenchymal neoplasm, predominantly affecting adolescents and young adults. "Four ARGs-BRMS, COL4A2, FGF2, and OGT-were used to develop an RFS-predicting model, whereas seven ARGs-CD24, FASN, MMP2, EIF2AK3, ID2, PPARG, and PIK3R3-were used to develop an OS-predicting model in patients with osteosarcoma." (PMID 38217543, 2024).
ovarian carcinoma (2 papers, 2020 to 2021). A malignant neoplasm originating from the surface ovarian epithelium. "Importantly, available ChIP-Seq data of MECOM in human ovarian carcinoma cells also showed direct binding to the promotor regions of Col4a2 and Itga2." (PMID 33762742, 2021). "It is also noticed that the origins of high COL1A1, COL1A2, and COL3A1 expression positively correlate with fibroblast-specific markers (FAP) and smooth muscle actin (ACTA2), whereas COL4A1, COL4A2, and COL18A1 seem to be predominantly expressed in ovarian cancer cells." (PMID 33026975, 2020).
psoriasis (2 papers, 2019 to 2024). An autoimmune condition characterized by red, well-delineated plaques with silvery scales that are usually on the extensor surfaces and scalp. "Communication between hair follicle cells and Langerhan cells was associated with COL4A2/CD44 and LAMC1/CD44 in psoriasis, contrasting with a relatively weak HBEGF/EGFR ligand-receptor pair in normal skin." (PMID 38289616, 2024). "Communication between hair follicles and mast cells, melanocytes, and myeloid cells only occurred in psoriasis, focusing on COL4A2/CD44 and APP/CD74 ligand-receptor pairs." (PMID 38289616, 2024).
Acidosis (1 paper, 2022). Abnormal acid accumulation or depletion of base. "COL4A2 was found among the top ten important genes in acidosis and the “Acidosis and Bone metastasis” overlap." (PMID 35159353, 2022). "Additionally, the top seven nodes of the “Acidosis” network were present among the top ten nodes of “Acidosis and Bone metastasis”: COL1A1, COL3A1, COL4A1, COL4A2, ITGB3, THBS2, and ITGA11." (PMID 35159353, 2022).
acute coronary syndrome (1 paper, 2022). Signs and symptoms related to acute ischemia of the myocardium secondary to coronary artery disease. "The aim of this case-control association study was to evaluate the associations between the occurrence of acute coronary syndromes in the form of unstable angina and SNPs within the PECAM1, COL4A2, PHACTR1 and LMOD1 genes." (PMID 35054067, 2022).
acute liver failure (1 paper, 2023). Rapid deterioration of liver function causing encephalopathy and coagulopathy. "In addition, prior research has demonstrated that COL4A2 is a possible biomarker for the diagnosis of acute liver failure." (PMID 37266443, 2023).
Adult onset (1 paper, 2024). Onset of disease manifestations in adulthood, defined here as at the age of 16 years or later. "Thus, reduced collagen IV levels increase the risk of late-onset ICH and kidney disease, and suggest common risk alleles in COL4A2 for sporadic adult-onset CSVD with ICH act by reducing collagen IV levels." (PMID 39216230, 2024).
Alport syndrome (1 paper, 2024). A rare renal disease characterized by glomerular nephropathy with hematuria progressing to end-stage renal disease (ESRD), frequently associated with sensorineural deafness, and occasionally with ocular anomalies. "Col4a2, Col4a3, and Col4a4 are associated with Alport's syndrome, a condition characterized by progressive hearing loss." (PMID 38413848, 2024).
aortic aneurysm (1 paper, 2023). A ruptured aneurysm located in the wall of the proximal portion of the descending aorta proceeding from the arch of the aorta. "Defects in the components of those pathways [Collagen Type IV Alpha 2 Chain (COL4A2), Collagen Type IV Alpha 1 Chain (COL4A1), Collagen Type VI Alpha 1 Chain (COL6A), Elastin (ELN)] were previously proposed to be associated with aortic aneurysm formation." (PMID 36922793, 2023).
Aortic dissection (1 paper, 2025). Aortic dissection refers to a tear in the intimal layer of the aorta causing a separation between the intima and the medial layers of the aorta. "Microarray data from the Sandmann group identified downregulation of COL4A2 and COL4A5 in aortic dissection." (PMID 41497804, 2025).
Arthritis (1 paper, 2021). Inflammation of a joint. "Structured literature searching of PubMed and Google Scholar databases identified Bhlhe40, Col4a2 and Pitx1 as the top-ranked candidate genes with publications related to arthritis or skeletal cell biology." (PMID 33473114, 2021).
astrocytoma (1 paper, 2021). "COL4A2 was significantly higher expressed in GBM than astrocytoma, which was confirmed by RT-qPCR." (PMID 34034744, 2021).
bleeding (1 paper, 2025). "Emerging evidence points to genetic factors, such as mutations in COL4A1 and COL4A2 genes, as relevant to neonatal intracranial bleeding." (PMID 40126707, 2025).
brain injury (1 paper, 2025). Acute and chronic (see also brain INJURIES, CHRONIC) injuries to the brain, including the cerebral hemispheres, CEREBELLUM, and brain STEM. "Previous studies on diseases such as cerebral hemorrhage and ischemic brain injury have demonstrated that mutations in COL4A2 may increase the vulnerability of cerebral blood vessels by disrupting the structure and function of collagen IV." (PMID 40539067, 2025).
brain malformations (1 paper, 2026). "In this study, we investigated two cases with severe cerebrovascular defects and brain malformations, identifying biallelic COL4A2 variants predicted to affect protein stability and function." (PMID 41499643, 2026). "In conclusion, our study emphasizes the critical role of biallelic COL4A2 variants in BSVD and severe brain malformations, significantly expanding the genotype and phenotype spectrum of recessive COL4A2‐related disorders." (PMID 41499643, 2026). "Biallelic variants in COL4A2 (MIM *120090), encoding the alpha‐2 chain of type IV collagen, are a major determinant of brain small vessel disease (BSVD) and various brain malformations." (PMID 41499643, 2026).
cardiomyopathy (1 paper, 2023). A disease of the heart muscle or myocardium proper. "The hub genes COL4A2/COL4A1/SMAD3 may be potential research targets for cardiomyopathy-associated MI." (PMID 38001896, 2023). "COL4A2/COL4A1/SMAD3 were the hub genes in pericyte function involved in cardiomyopathy and AMI." (PMID 38001896, 2023).
cerebral cavernous malformation (1 paper, 2024). A disorder characterized by malformations in the structure of the capillaries in the brain. "The disorders we identified were Moyamoya disease (MMD), COL4A1, COL4A2 pathogenic variant, Ehlers–Danlos syndrome (E-D), neurofibromatosis type 1 (Nf1), sickle cell disease (SCD), cerebral cavernous malformations (CCM), hereditary hemorrhagic telangiectasia (HHT) and Marfan syndrome." (PMID 38790247, 2024).
cerebral infarction (1 paper, 2023). An ischemic condition of the brain, producing a persistent focal neurological deficit in the area of distribution of the cerebral arteries. "The first is the duplication of both the COL4A1 and (partial) COL4A2 genes in a affected individual (AD8) with multiple cerebral infarctions leading to neurological problems including movement disorders and speech problems." (PMID 36781956, 2023).
congenital diaphragmatic hernia (1 paper, 2016). A posterolateral defect of the diaphragm that allows passage of abdominal viscera into the thorax, leading to respiratory insufficiency and persistent pulmonary hypertension with high mortality. "The phenotype observed in Col4a1 and Col4a2 mutants is characterized by a block between the saccular and alveolar stages reminiscent of the severe abnormalities of premature newborns and children with congenital diaphragmatic hernia." (PMID 27412481, 2016).
corneal dystrophies (1 paper, 2020). "Other candidates genes include transforming growth factor beta-induced (TGFBI) or zinc-finger E-box binding homeobox 1 (ZEB1), involved in corneal dystrophies or COL4A1, COL4A2, COL4A2, and COL4A1, encoding collagen proteins responsible for the proper function of the cornea." (PMID 32879808, 2020).
cyst (1 paper, 2014). A sac-like closed membranous structure that may be empty or contain fluid or amorphous material. "While sequence analysis of patient IV:21, who has a large porencephalic cyst, excluded COL4A1 mutations, it identified a base pair change in exon 28 of COL4A2 that is predicted to substitute a glycine residue of a Gly-X-Y repeat for aspartic acid (G702D)." (PMID 24001601, 2014).
diabetic nephropathy (1 paper, 2022). "COL4A1 is involved in diabetic nephropathy while COL4A2 is involved in diabetic cardiovascular disease development." (PMID 36118693, 2022).
endometriosis (1 paper, 2025). The growth of functional endometrial tissue in anatomic sites outside the uterine body. "We have found upregulated COL4A2 expression in deep endometriosis compared to healthy endometrium." (PMID 40135061, 2025). "Moreover, a significant downregulation of several potential targets, including CDK6, BCCIP, PTEN, TCF7L1, TCF7L2, ROBO1, COL4A2, E‐Cadherin, and N‐Cadherin, was observed in the transfected cells and endometriosis patients." (PMID 40135061, 2025).
Fabry disease (1 paper, 2025). Fabry disease (FD) is a progressive, inherited, multisystemic lysosomal storage disease characterized by specific neurological, cutaneous, renal, cardiovascular, cochleo-vestibular and cerebrovascular manifestations. "When viewed together, differential methylation of COL4A1 and COL4A2 genes suggests an association with cerebrovascular vulnerability in males with Fabry disease." (PMID 41150803, 2025). "Most notably, evidence suggesting a causal relationship between altered methylation of COL4A1 and COL4A2 genes and cerebrovascular pathologies in Fabry disease remains to be firmly established." (PMID 41150803, 2025). "In the current study, preliminary evidence suggests that decreased methylation of COL4A1 and COL4A2 may play a role in disrupting blood vessel architecture and contribute to vasculopathy in individuals with Fabry disease." (PMID 41150803, 2025).
factor VII deficiency (1 paper, 2021). A coagulation disorder characterized by the partial or complete absence of factor VII activity in the blood. "We collected data on: hemostatic genes (factor V deficiency, von Willebrand’s disease, factor VII deficiency), protrombothic genes (factor V Leiden, MTHFR mutation, protein C deficiency), collagen genes (COL4A1 and COL4A2 mutations), and X linked GATA1 gene mutation." (PMID 33920939, 2021).
infantile epileptic spasm syndrome (1 paper, 2024). "This study focused on Col4a2-related infantile epileptic spasm syndrome and revealed incomplete penetrance of the Col4a2 gene mutation." (PMID 39006838, 2024). "Genetic analysis revealed eight missense mutations related to Col4a2 infantile epileptic spasm syndrome, seven of which are likely pathogenic and the other one is of uncertain significance." (PMID 39006838, 2024). "In this study, we retrospectively analyzed eight patients who were initially diagnosed with Col4a2-related infantile epileptic spasm syndrome and discovered elevated proinflammatory cytokine levels in the cerebrospinal fluid." (PMID 39006838, 2024). "A total of 8 patients aged 2 years and 2 months to 18 years who were diagnosed with Col4a2-related infantile epileptic spasm syndrome were analyzed." (PMID 39006838, 2024). "To explore the role of Col4a2 mutations in epileptogenesis, we first conducted a retrospective analysis of eight patients who were diagnosed with Col4a2-related infantile epileptic spasm syndrome." (PMID 39006838, 2024).
leiomyoma (1 paper, 2013). A well-circumscribed benign smooth muscle neoplasm characterized by the presence of spindle cells with cigar-shaped nuclei, interlacing fascicles, and a whorled pattern. "Collagen-related genes such as COL4A1 and COL4A2 have been previously reported to be upregulated in leiomyomas." (PMID 23818951, 2013). "The genes associated with “cancer process” contained potentially novel or relevant candidate genes for leiomyoma formation such as IRS1, COL4A1, COL4A2, COL6A3, and GSTM5." (PMID 23818951, 2013). "IRS1 is also reported to be involved in the upregulation of collagen genes, including COL4A1, COL4A2 and COL6A3, suggesting that IRS1 possibly contributes to the leiomyoma nodule formation by upregulating the gene expression of COL4A1, COL4A2, and COL6A3." (PMID 23818951, 2013).
lumbar disc degeneration (1 paper, 2025). "Analysis of the training set revealed that the expression levels of the cell cycle regulatory gene CDK1 and the extracellular matrix gene COL4A2 were significantly elevated in patients with lumbar disc degeneration compared to controls." (PMID 41409278, 2025).
meningioma (1 paper, 2022). A generally slow growing tumor attached to the dura mater. "We found that the expression of COL2A1, and COL9A3 were significantly upregulated in meningioma tissues, and the expression of COL14A1, COL4A3, and COL4A2 was significantly down-regulated." (PMID 36538194, 2022).
mitochondrial DNA depletion syndrome (1 paper, 2023). The mitochondrial DNA (mtDNA) depletion syndrome (MDS) is a clinically heterogeneous group of mitochondrial disorders characterized by a reduction of the mtDNA copy number in affected tissues without mutations or rearrangements in the mtDNA. "We had only two patients who underwent NGS and found variants in other disease-related genes, one case with TK2-related mitochondrial DNA depletion syndrome, myopathic form (TK2-MDS), and one with COL4A2-associated myopathy." (PMID 38002481, 2023).
nasopharyngeal carcinoma (1 paper, 2010). A carcinoma arising from the nasopharyngeal epithelium. "Mir-29c was reported to be under expressed in nasopharyngeal carcinomas and up regulated genes COL4A1, COL4A2 and TDG." (PMID 21114830, 2010).
Nephropathy (1 paper, 2016). A nonspecific term referring to disease or damage of the kidneys. "Mutations in the ubiquitous human BM components COL4A1 and COL4A2 cause a multisystem disorder involving nephropathy." (PMID 27077087, 2016).
neuroma (1 paper, 2022). A tumor that grows from a nerve or is composed of nerve cells and nerve fibers. "Using the provided data as reference enabled us to objectively diagnose CN abnormalities, such as abnormal formation of CN3 (Col4a2), neuroma of the motor portion of CN5 (Arid1b), thinning of CN7 (Rpgrip1l) and abnormal topology of CN12 (Cc2d2a)." (PMID 36438572, 2022).
otosclerosis (1 paper, 2023). Formation of spongy bone in the labyrinth capsule which can progress toward the stapes (stapedial fixation) or anteriorly toward the cochlea leading to conductive, sensorineural, or mixed hearing loss. "Future mechanistic studies could examine whether COL4A2 has a structural or signaling role in otosclerosis." (PMID 36653343, 2023).
ovarian endometriosis (1 paper, 2025). A non-neoplastic disorder characterized by the growth of endometrial tissue in the ovaries. "Consistent with our findings, COL4A2 is upregulated in ovarian endometriosis compared to healthy ovarian tissues." (PMID 40135061, 2025).